CD47 (CD47 molecule)
Diseases named in the same sentence as CD47 in open-access papers (continued):
Sharing a sentence is not in itself a finding about the gene and the disease.
glioma (continued). "When we treated murine glioma cells with an anti-mouse-CD47 mAb (clone MIAP410) known to functionally inhibit murine CD47–SIRPα interactions, we only observed a 10–20% increase in tumor cell phagocytosis by bone marrow (BM)-derived phagocytes." (PMID 32198351, 2020). "We found that when TMZ was given with anti-CD47 antibody, a significantly higher degree of glioma cell phagocytosis was observed as compared to either treatment alone." (PMID 32198351, 2020). "Targeting the phagocytosis checkpoint CD47 using a humanized anti-CD47 antibody, Hu5F9-G4, has shown promise in a glioma PDX mouse model of five aggressive pediatric brain cancers." (PMID 33154756, 2020). "Glioma cells can evade phagocytosis by upregulating anti-phagocytosis molecule CD47; however, CD47 blockade alone is inefficient in stimulating glioma cell phagocytosis by macrophages." (PMID 33374253, 2020). "Conversely, the inhibition of β-catenin in mutant glioma cells abrogated CD47 expression as well as the interaction between β-catenin and TCF4." (PMID 31921125, 2019). "We conclude that the promotion of M1 macrophages represents an opportunity to enhance the anti-glioma effect achieved by anti-CD47 monoclonal antibodies, which also promote the classical (M1) phenotype of macrophages." (PMID 27092773, 2016). "This suggests that HIF-1α may contribute to glioma's malignant progression by upregulating CD47 expression." (PMID 39781344, 2025). "Our study further reveals that CD47 can serve as a biomarker for patients with the GMC-I subtype of glioma, and modulating CD47 molecules may reverse the poor prognosis of the GMC-I subtype, providing guidance for clinical treatment." (PMID 40129966, 2025). "Although anti-CD47 showed promising results in preclinical studies, their therapeutic effects could be limited by the pattern of CD47 expression in glioma patients, especially newly diagnosed subjects." (PMID 38786045, 2024). "Thus, we interrogated the combinatorial benefit of DCA and CD47 targeting in an immunocompetent syngeneic tumor model utilizing mouse CT2A glioma cell implantation in the mouse brain." (PMID 39545414, 2024). "Recombinant anti‐CD47 monoclonal antibodies, when admixed within subsurface‐injected hydrogel solutions, demonstrated cytotoxic activity against an infiltrative high‐grade glioma xenograft." (PMID 39553428, 2024). "In addition to reprogramming of TAMs, glioma cells can upregulate the antiphagocytic “don’t eat me” surface protein CD47, which binds to its receptor signal-regulatory protein alpha (SIRP⍺) on TAMs and inhibits their phagocytic activity." (PMID 38254796, 2024). "Combination therapies with other immune checkpoint inhibitors, such as anti-CD47, which has shown promising results in adult and pediatric gliomas, may also be of benefit." (PMID 38254796, 2024). "Furthermore, the CD47/SIRPα axis expression in the mouse glioma model was consistent with that in clinical patients." (PMID 39713206, 2024). "On the other hand, the classical monocytes had lower expression of SIRPalpha than intermediate and non-classical cells which suggests that classical monocytes are less able to interact with CD47 and thus less sensitive to induce an antiphagocytic signal in glioma patients." (PMID 36768201, 2023). "Besides targeting CD47 in glioma cancer immunotherapy, the GD2-directed chimeric antigen receptor (CAR) T cells are also in phase I clinical trial (NCT04196413)." (PMID 37063864, 2023). "Notably, monotherapeutic anti-CD47 antibodies show a minor effect on glioma growth in murine models but induce hematological toxicity." (PMID 36594466, 2023). "In addition, in an immunocompetent mouse glioma model, blocking the CD47-SIRPα axis by anti-CD47 antibody significantly increased phagocytosis of glioma cells and GSCs by macrophages, consequently inhibiting tumor growth and prolonging survival." (PMID 35967394, 2022).
glioma (continued). "It was worth noting that curcumin could reduce CD47 expression on the irradiated glioma cell surface, alleviate the “don't eat me” signal, and help to activate a stronger immune response." (PMID 36238646, 2022). "However, CD47 blockade alone is inefficient in stimulating glioma cells phagocytosis by TAMs and has limited anti-tumor effects." (PMID 35967394, 2022). "In addition, CD47 on cell membrane was declined after combination treatment in normoxic and hypoxic glioma compared to IR alone." (PMID 36238646, 2022). "CD47 is overexpressed in glioma cells and can block phagocytosis by macrophages." (PMID 36466873, 2022). "In contrast, IDH1 (R132H) mutation in gliomas, negatively regulates CD47 gene transcription, which disrupts the binding of PKM2/β-catenin/BRG1 complex to TCF4 transcription factor resulting in inhibition of TCF4-mediated CD47 expression." (PMID 34512146, 2021). "It was demonstrated disrupting the CD47-SIRPα axis could exert antitumor effects on gliomas, and malignant pediatric brain tumors." (PMID 33815356, 2021). "Moreover, preclinical studies based on orthotopic glioma models showed that blocking CD47 using antibodies decreased tumor growth and enhanced animal survival." (PMID 34168976, 2021). "Using mouse glioma models which enable the differentiation of genetically labelled MDM (Ccr2 RFP) and MG (Cx3cr1 GFP), they showed that microglia associated tumor cells increase tumor cell phagocytosis in response to CD47/SIRPA axis inhibition." (PMID 34168976, 2021). "The first is that exosomes excreted as waste by glioma cells may express a ligand, e.g., CD47, that prevents their reuptake." (PMID 33407703, 2021). "Indeed, the resident MG is capable of phagocytosis when meeting with glioma cells in response to myeloid checkpoint CD47- Signal regulatory proteinα (SIRPα) blockade in vivo." (PMID 34671362, 2021). "Here, we show that CD47 blockade alone is inefficient in stimulating glioma cell phagocytosis." (PMID 32198351, 2020). "CD47-targeting therapies have extensive preclinical validation, and targeting CD47 with monoclonal antibodies (MAbs) in xenograft models of ovarian, colon, breast, bladder, lung, pancreatic carcinoma, glioma, and leiomyosarcoma enhances macrophage activity and tumor elimination." (PMID 31276567, 2019). "However, anti-CD47 therapy provides a unique means of targeting gliomas by taking advantage of local TAMs and enhancing the M1 macrophage presence and response." (PMID 27092773, 2016). "Several studies have indicated anti-CD47 therapeutics may be a viable strategy for glioma." (PMID 38786045, 2024). "Targeting the CD47-SIRPα immune checkpoints has emerged as a promising strategy in both preclinical and clinical studies, with the potential to modify the tumor microenvironment, restore innate and adaptive immune functions, and enhance the prognosis of gliomas." (PMID 38956740, 2024). "CD47 deletion may reduce the stemness properties of glioma CSCs." (PMID 35740975, 2022). "Preclinical studies of anti-CD47 therapies for glioma have shown that, while anti-CD47 therapy is sometimes effective at stimulating glioma cell phagocytosis, chemotherapy and radiotherapy are synergistic with treatment and may be required to enhance phagocytosis and extend survival in mice." (PMID 34298615, 2021). "However, very recently, it was shown that TNC increases glioma cell phagocytosis when CD47 surface marker is lost in a GBM xenograft mouse model, and the authors correlated the increased TNC levels to a potential defensive mechanism by the immune system against the tumor." (PMID 33766119, 2021). "In the brains of glioma‐bearing mice, B‐LNP blocks CD47 and enhances the phagocytic activity of TAMs, promoting tumor regression." (PMID 41403915, 2025). "Some other immune checkpoints, including CTLA-4, CD47, CD73, TIGIT, and CD137 were also studied in either clinical trials or preclinical research for gliomas." (PMID 39851525, 2025).
glioma (continued). "Importantly, lactylation modification played a key role in the glioma microenvironment, for example, lactate induced epigenetic reprogramming of glioma cells through histone lactylation, which led to transcriptional upregulation of CD47 to inhibit phagocytosis and promote immune evasion." (PMID 41035644, 2025). "mIAP301, an anti-CD47 mAb that blocks the binding between murine CD47 and SIRPα, has been shown to enhance phagocytosis of GL261 glioma cells and glioma stem cells by macrophages and prolonged mouse survival." (PMID 38786045, 2024). "The expression of the more well-known immune-related targets in glioma, such as CTLA4, PDCD1 (PD-1), CD274 (PD-L1), LAG-3, and CD47, was then examined." (PMID 38396140, 2024). "Several well-characterized oncogenic pathways have recently been shown to regulate CD47 expression in GBM cells and glioma stem cells (GSCs) including Epidermal Growth Factor Receptor (EGFR) beta catenin." (PMID 39194679, 2024). "In the analysis of CD47/SIRPα as a function of WHO grade, SIRPα expression is significantly reduced in grade 4 gliomas." (PMID 38786045, 2024). "Combination treatment of an anti-CD47 antibody and temozolomide induced ER stress, activated the STING pathway, and increased glioma cell phagocytosis by APCs, resulting in increased antigen cross-presentation and T cell priming." (PMID 38226619, 2024). "The metabolic rewiring from glycolysis to fatty acid oxidation (FAO) upregulates the expression of CD47 by the acetylation of NF-kB/RelA, and correspondingly, the FAO promotes the glioma growth with CD47-mediated immune escape." (PMID 37063864, 2023). "In our study, Siglec15 was broadly and positively correlated with immune checkpoints that have been reported as potential biomarkers of glioma, such as PD1, PDL1, PDL2, Lag3, CTLA4, TIGIT, CD276 (B7-H3), IDO1 and CD47." (PMID 37325664, 2023). "Recently, research demonstrated that anti-CD47 strategies show promising antitumor effects in various gliomas, including GBM 108 and pediatric glioma 109, by increasing TAM-mediated phagocytosis of macrophages." (PMID 37705736, 2023). "Owing to the specific role of QPCTL in the binding between CD47 and SIRPα, targeting QPCTL instead of targeting CD47 in gliomas overcomes the side effects of targeting CD47." (PMID 37063864, 2023). "Blockage of the anti-phagocytic CD47-SIRPα axis using an anti-CD47 antibody, Hu5F9-G4, strongly induced BMDM-mediated phagocytosis of glioma cells, and mice treated with Hu5F9-G4 demonstrated significant longer survival (Molecular event 9)." (PMID 36555253, 2022). "To do so, we cocultured cOVA-expressing murine glioma cells treated with TMZ and anti-CD47 antibody with BM APCs." (PMID 32198351, 2020). "Immunohistochemistry analysis revealed that the vast majority of 78 paraffin-embedded archival glioma specimens tested displayed positive CD47 expression, CD147 had stronger staining in high-grade glioma tissues than low grade glioma tissues." (PMID 33178600, 2020). "Our data show that THBS1 is not only involved in the regulation of angiogenesis in GBM, but also impacts the invasive behaviour of glioma cells and that THBS1/CD47 interactions contributes to this process." (PMID 30850588, 2019). "Glioma cells are known to upregulate the expression of the surface protein CD47, which acts as a ‘do not eat me’ signal, inhibiting phagocytosis by binding to its receptor SIRPα on MDM and MG." (PMID 40845580, 2025). "However, the expression levels of IL‐12, CD47, and SLAMF7 were higher in tumors than in adjacent non‐tumorous tissues, as determined by analyzing their mRNA expression levels in glioma patients using TCGA and GTEx datasets." (PMID 39713206, 2024). "In another study, the use of a temperature-sensitive hydrogel system hydroxypropyl chitin (HPCH) copolymer which encapsulates both anti-CD47 and TMZ was able to provide a full curative effect in approximately 50% of the animals harboring GL261 murine glioma tumors." (PMID 39194679, 2024).
glioma (continued). "We intracranially injected luciferase‐expressing CT‐2A mouse glioma cells with or without knock‐in expression of CD47 Y286F or CD47 K99/102R." (PMID 37541303, 2023). "Another research found the CD47/SIRPα axis as a “do not eat me signal” of glioma and blocking CD47 effectively restraining the glioma progression." (PMID 37849438, 2023). "CD47 expression is high in GBM and stem cells and is positively correlated with glioma grade." (PMID 35954362, 2022). "CD47 is a transmembrane glycoprotein, acting as a “do not eat me” antiphagocytic signal; its high expression is a negative prognostic marker in gliomas, and the inhibition of CD47 in different cancer models suppresses tumor growth." (PMID 35628503, 2022). "In terms of combination of immunotherapy, the CD47 antibody that focuses on re‐education of TA‐MG and TA‐MAC needs to be combined with other immunotherapy such as dendritic vaccines and adoptive T‐cell therapy to treat gliomas." (PMID 34363319, 2021). "Since CD47 blockade and TMZ promote glioma cell phagocytosis by BM cells through distinctive mechanisms, we next investigated whether they can be combined to produce more potent phagocytic effects." (PMID 32198351, 2020). "By conducting Pearson correlation analysis on glioma samples from the CGGA and TCGA databases, it was discovered that the expression of SOCS1 is significantly positively correlated with several known inhibitory immune checkpoints, including HVEM, TIM-3, PD-1, PDCD2, TIGIT, CD200R1, CTLA4, and CD47." (PMID 39654174, 2024). "Though the anti‐CD47 therapy did not concern the re‐education of microglia and failed in the pre‐clinical stage, the enhanced phagocytosis was proved an effective target in glioma treatment." (PMID 37849438, 2023). "To examine whether inhibition of CD47 can sensitize the inhibitory effect of EGFR inhibitors on tumor growth, we treated the mice bearing the brain tumor derived from CT‐2A glioma cells with EGFR inhibitor afatinib or an anti‐CD47 antibody alone or with a combination of both reagents." (PMID 37541303, 2023). "Another study showed that the CD47 blockade alone could not stimulate glioma cell phagocytosis in human and murine, but that the CD47 blockade combined with TMZ significantly impacted pro-phagocytosis in murine and human GBM cells." (PMID 35954362, 2022). "CRACD mRNA expression inversely correlated with IFT57 mRNA and with survival in low-grade gliomas, lung adenocarcinomas, and papillary thyroid carcinomas, suggesting that IFT57 rather than CD47 regulates survival in these cancers." (PMID 39201643, 2024).
leukemia (82 papers, 2012 to 2026). A malignant (clonal) hematologic disorder, involving hematopoietic stem cells and characterized by the presence of primitive or atypical myeloid or lymphoid cells in the bone marrow and the blood. "In fact, among the cancer types studied, leukemia is the most susceptible to the anti-CD47 antibody treatment." (PMID 38920727, 2024). "By inhibiting the “don’t-eat-me” signal, the anti-CD47 antibody causes phagocytosis of leukemia cells, eradicates T cell acute lymphoblastic leukemia engraftment, and leads to disease remission in a mouse model of leukemia." (PMID 36059451, 2022). "Accordingly, restoration of CD47 expression in CD47-deficient leukemia cells increases xenograft aggressiveness." (PMID 26578962, 2015). "As previously suggested, it must be underlined that CD47 is also widely expressed in normal cells, and this might increase off-target toxicity when CD47 is considered to be a therapeutic target in leukemia." (PMID 37371818, 2023). "The overexpression of CD47 on leukemia cells (LSCs) and hematopoietic stem cells (HSCs) assists in evading phagocytosis." (PMID 40647402, 2025). "In another experiment, miR-708-overexpressed CCRF-CEM cells were incubated with macrophages derived from THP-1 (human leukemia monocytic cell line) and with anti CD47 antibody." (PMID 38339019, 2024). "First, why is there a differential therapeutic efficacy of the CD47/SIRPA blockade in leukemia vs. solid tumors?" (PMID 38920727, 2024). "As higher expression of CD47 on AML leukemia stem cells promotes AML immune evasion from phagocytes and correlates with worse overall survival, this increase in CD47 suggests an intrinsic protective response to DHODHi." (PMID 38646934, 2024). "CD47 expression is higher in leukemia stem cells (LSCs) compared to normal progenitor counterparts, allowing LSCs to evade elimination by phagocytosis." (PMID 39199554, 2024). "“In vitro” data with anti-CD47 antibodies confirmed the selective reduction in LSCs; in mice models, the failure of leukemia transplant in secondary recipients demonstrated LSC depletion/dysfunction." (PMID 37371818, 2023). "In contrast, TSP-1-induced cell death in leukemia, lung, breast, and colon cancer cell lines in a CD47-dependent, caspase-independent manner." (PMID 37958404, 2023). "SIRPα/CD123 BsAb also established its safety by demonstrating low CD47-related on-target off-leukemia toxicity." (PMID 35978372, 2022). "Given the rapid emergence of new targeted anti-leukemia therapies, such studies should be further expanded to CD47 macrophage checkpoint inhibitors and the growing number of anti-leukemic small molecules with potential implications for antifungal immunity." (PMID 36389687, 2022). "Targeting the CD47/SIRPα, Hu5F9-G4 antibody has been used in combination with Azacitidine, and the results have shown promising effects in leukemia stem cells (NCT03248479)." (PMID 35395787, 2022). "Human CD47 cross-dressing protects not only xenogeneic pig cells, but also human leukemia cells, against phagocytosis by human macrophages." (PMID 36454036, 2022). "In preclinical studies, CD47-SIRPα inhibition resulted in improved phagocytic activity and better control of leukemia." (PMID 34944878, 2021). "Several therapeutic strategies to target CSCs have emerged, such as the development of a bispecific antibody that brings cytotoxic T cells to CD133+ CSCs in pancreatic and hepatic cancers and blockade of CD47 to target CSCs in leukemia." (PMID 35046949, 2021). "CD47-B is a fully human IgG1 anti-CD47 mAb which have increased phagocytosis of CD47-expressing cells by human macrophages and demonstrated anti-tumor activity in leukemia mouse models." (PMID 34584838, 2021).